SST (somatostatin)
Description:
[Somatostatin-14]: Inhibits the secretion of pituitary hormones, including that of growth hormone/somatotropin (GH1), PRL, ACTH, luteinizing hormone (LH) and TSH. Also impairs ghrelin- and GnRH-stimulated secretion of GH1 and LH; the inhibition of ghrelin-stimulated secretion of GH1 can be further increased by neuronostatin. [Neuronostatin]: May enhance low-glucose-induced glucagon release by pancreatic alpha cells (By similarity). This effect may be mediated by binding to GPR107 and PKA activation (By similarity). May regulate cardiac contractile function (By similarity). May compromise cardiomyocyte viability (By similarity). In the central nervous system, may impair memory retention and may affect hippocampal excitability (By similarity). May also have anxiolytic and anorexigenic effects (By similarity). May play a role in arterial pressure regulation (By similarity). May inhibit basal, but not ghrelin- or GnRH-stimulated secretion of GH1 or LH, but does not affect the release of other pituitary hormones, including PRL, ACTH, FSH or TSH. Potentiates inhibitory action of somatostatin on ghrelin-stimulated secretion of GH1, but not that on GnRH-stimulated secretion of LH.
Synonyms: SMST; SST1
Tractability: Small molecule: a structure with a bound ligand is known. Antibody: its Gene Ontology location is reachable by antibodies, with high confidence; UniProt places it where antibodies can reach, with medium confidence; UniProt predicts a signal peptide or a membrane-spanning region. PROTAC: its protein half-life has been measured.
Gene: Protein-coding gene on chromosome 3 (187,668,912 to 187,670,394, reverse strand). Ensembl gene ENSG00000157005.
Subcellular location: Secreted
Pathways (Reactome):
Signal Transduction: G alpha (i) signalling events; Peptide ligand-binding receptors
Gene Ontology:
Molecular function: protein binding; hormone activity; receptor ligand activity
Biological process: cell surface receptor signaling pathway; cell-cell signaling; chemical synaptic transmission; digestion; G protein-coupled receptor signaling pathway; hormone-mediated apoptotic signaling pathway; negative regulation of cell population proliferation; regulation of cell migration; response to nutrient; hyperosmotic response; regulation of postsynaptic membrane neurotransmitter receptor levels; response to acidic pH; response to amino acid; response to steroid hormone; response to xenobiotic stimulus; somatostatin signaling pathway
Cellular component: extracellular region; cytosol; GABA-ergic synapse; neuronal cell body; neuronal dense core vesicle
Genetic constraint (gnomAD): Loss-of-function variants: 7 observed, 8.47 expected, observed/expected ratio (o/e) 0.83, 90% interval 0.47 to 1.53. That is too few expected variants to judge how well the gene tolerates losing a copy. Missense variants: 145 observed, 132.65 expected, observed/expected ratio (o/e) 1.09, 90% interval 0.95 to 1.25. Synonymous variants: 63 observed, 58.32 expected, observed/expected ratio (o/e) 1.08, 90% interval 0.88 to 1.33.
Homologues: Orthologues: chimpanzee SST (99% identical), macaque SST (99% identical), pig SST (99% identical), dog SST (98% identical), rabbit SST (98% identical), guinea pig SST (97% identical), mouse Sst (97% identical), rat Sst (97% identical), tropical clawed frog sst (74% identical), zebrafish sst1.1 (69% identical), zebrafish sst1.2 (44% identical), zebrafish sst2 (25% identical).
Diseases named in the same sentence as SST in open-access papers:
SST is named in the same sentence as 340 diseases in open-access papers, as found by Europe PMC text mining. Sharing a sentence is not in itself a finding about the gene and the disease. The quoted sentences say what the papers report.
neuroendocrine tumors (82 papers, 2012 to 2026). "Peptide receptor radionuclide therapy (PRRT) involves linking the radionuclide lutetium-177 to a targeting somatostatin analog, and it is effective in treating a variety of neuroendocrine tumors." (PMID 40565361, 2025). "Although this study included only 4 patients, it provides the first clinical evidence that radiolabeled SST antagonists were superior to SST agonists in treating neuroendocrine tumors." (PMID 40943459, 2025). "Beyond LHRH, Schally’s contributions to the development of somatostatin analogs have also had a significant impact on the management of acromegaly and neuroendocrine tumors." (PMID 39398731, 2024). "Meanwhile, the use of radiolabeled somatostatin analogs for peptide receptor radionuclide therapy (PRRT) has also achieved good efficacy in the treatment of neuroendocrine tumors." (PMID 38877554, 2024). "For those with metastatic R‐NENs, systemic treatments used for other neuroendocrine tumours such as peptide‐receptor radio nucleotide therapy, tyrosine kinase inhibitors, somatostatin analogues and chemotherapy are often considered." (PMID 38873350, 2024). "Synthetic SST analogs that have a much longer half-life than the endogenous SST are more useful in the management of acromegaly and numerous neuroendocrine tumors." (PMID 37111609, 2023). "The discovery of somatostatin and its role in hormonal regulation has increased our knowledge of neuroendocrine tumors." (PMID 38201544, 2023). "In most neuroendocrine tumours, the expression of SSTR subtypes at the tumour site is associated with an SST-mediated antitumour role, supporting the role of SST as an endogenous inhibitor of cell proliferation." (PMID 38203605, 2023). "Acromegaly and neuroendocrine tumors are rare diseases that, under certain conditions, can be treated with somatostatin analogs." (PMID 35913681, 2023). "This study will help in the design of new somatostatin-based compounds for theranostics of neuroendocrine tumours." (PMID 36959237, 2023). "Certain tissues and tumors, including neuroendocrine tumors, express receptors that bind to hormones, including somatostatin." (PMID 37568733, 2023). "Due to the fact that somatostatin regulates cell growth and hormone secretion, somatostatin receptors (SSTRs) have become valuable targets for the treatment of different types of neuroendocrine tumours (NETs)." (PMID 35163374, 2022). "While its role is confirmed in acromegaly and neuroendocrine tumors, the research concerning somatostatin, the thymus, and thymic tumors seems to be exhausted." (PMID 35159040, 2022). "Lutetium-177 (177Lu) dotatate is a type of peptide receptor radioligand therapy (PRRT) using radiolabeled somatostatin for patients with progressive somatostatin receptor-positive gastrointestinal neuroendocrine tumors." (PMID 35371754, 2022). "SST analogs such as Octreotide and Lanreotide are currently used for the treatment of multiple diseases, including certain cancers (particularly neuroendocrine tumors), which supports a role for SST in downregulating pro-tumorigenic processes in the pancreas." (PMID 35574446, 2022). "Peptide receptor radionuclide therapy with radiolabeled somatostatin analogs is an innovative treatment for advanced somatostatin‐positive neuroendocrine tumors." (PMID 34174175, 2021). "Peptide receptor radionuclide therapy (PRRT) with radiolabeled somatostatin analogs is an innovative treatment for advanced somatostatin‐positive neuroendocrine tumors (NETs)." (PMID 34174175, 2021). "Nuclear imaging of somatostatin receptor (SST)-expressing tumors is established for the detection of neuroendocrine tumors (NETs) and their metastases." (PMID 32757150, 2020). "Microscopy and immunohistochemistry uncovered a neuroendocrine tumor, staining positive for chromogranin A (CgA), synaptophysin and somatostatin, with a Ki67 = 1%." (PMID 32825782, 2020).
neuroendocrine tumors (continued). "Somatostatin receptor (SST) targeting, specifically of the subtype 2 (SST2), with radiolabeled somatostatin analogs, is established for imaging and treatment of neuroendocrine tumors." (PMID 32757150, 2020). "First clinical results for this somatostatin antagonist theranostic pair seem to be promising with high sensitivity for neuroendocrine tumors and require further studies in larger patient population." (PMID 32887456, 2020). "Anlauf and his co-authors found that 13/28 (46.4%) duodenal gastrin-producing neuroendocrine tumors and 2/5 (40%) somatostatin-secreting neuroendocrine tumors revealed LOH of 11q13 from six patients with Zollinger–Ellison syndrome and MEN1." (PMID 32126984, 2020). "Neuroendocrine tumors normally express somatostatin (SST) receptors (SSTR) on cell surface, especially G1 and G2 stage tumors, but they can show a dedifferentiation in their clinical history as they become more aggressive." (PMID 31337043, 2019). "Evidence for somatostatin secretion by liver tumours is very rare, and usually, somatostatin‐positive neuroendocrine tumours are derived from the pancreas and the duodenum." (PMID 31592116, 2019). "Currently, a clinically relevant anti-tumor effect of SST analogues has been clearly demonstrated in advanced neuroendocrine tumors and SST analogues are generally accepted as therapy for these tumors." (PMID 31569719, 2019). "A classic development during this period, a radiolabelled peptide analog of somatostatin (SST) was used to target neuroendocrine tumors expressing the SST receptor instead of targeting the receptor with an antibody." (PMID 31091705, 2019). "Somatostatin are receptors that are expressed in various normal and neoplastic tissues, of which expression in neuroendocrine tumors is best characterized." (PMID 31569719, 2019). "A diagnosis of a somatostatin‐secreting neuroendocrine tumour with postprandial hypoglycaemia, mild diabetes mellitus and cholecystolithiasis was made." (PMID 31592116, 2019). "In contrast, somatostatin (SST) inhibits the secretion of autocrine growth factors from neuroendocrine tumors (NETs) and decreases proliferation." (PMID 30008698, 2018). "Unfortunately, and although SST analogs are widely used for the control of several types of tumors (e.g., pituitary and neuroendocrine tumors), clinical trials in humans with breast tumors using SST analogs have been inconclusive and unsuccessful." (PMID 26956474, 2016). "The synthetic somatostatin analogue, octreotide, has a longer half-life than native somatostatin, and is effective in inhibition of multiple tumors such as neuroendocrine tumors, gastrointestinal cancer, breast cancer and leukemia." (PMID 27825139, 2016). "Most neuroendocrine tumors (NETs) have high expression levels of SSTRs, which opens the possibility for tumor imaging and therapy with radiolabeled SST analogs." (PMID 25879040, 2015). "Application of SST analogues is widespread regarding the diagnosis and therapy of neuroendocrine tumors." (PMID 25723531, 2015). "The primary indication of SST-analogues imaging is for neuroendocrine tumors (NETs), which usually express a high density of SSTR, so they can be effectively targeted and visualized with radiolabeled SST-analogues in vivo." (PMID 24693229, 2014). "In Australia, for example, the recent Medicare coverage (government funding) approval for 177Lu-DOTATATE therapy included a provision for use in neuroendocrine tumors or other tumors with higher somatostatin expression (e.g., renal cell carcinoma, breast cancer, meningioma)." (PMID 41344832, 2025). "In addition, somatostatin analog (SSA) is the analog of SST which is now widely used in the treatment of neuroendocrine neoplasms." (PMID 36072337, 2022). "Lastly, immunosurveillance in neuroendocrine neoplasm is positive regulated by SST." (PMID 36072337, 2022). "In addition to its pivotal role in physiological processes, the SST-system also plays an important role in neuroendocrine tumors (NETs)." (PMID 33085037, 2021).
neuroendocrine tumors (continued). "After the radiolabeled somatostatin peptide analogues have being used successfully in neuroendocrine tumors for nuclear imaging and therapy, GRPR radioprotections (GRPR radiolagind) have been synthesized and used in preclinical and clinical studies, currently including the prostate." (PMID 33854977, 2021). "From these pre-clinical data and the beneficial effect of SST analogues in the treatment of neuroendocrine tumors, it was proposed that SST analogues could have a role in the management of inoperable HCC." (PMID 31569719, 2019). "In some studies, 68-Gallium DOTATATE peptide PET-CT -a type of functional imaging in which a radioisotope-labeled somatostatin analog peptide binds to the somatostatin receptor found in carcinoid– has been found to improve the anatomic localization of neuroendocrine tumors." (PMID 31477066, 2019). "Moreover, therapy using radiolabeled SST analogs is commonly used as a therapeutic option for the treatment of metastatic or inoperable neuroendocrine tumors." (PMID 30193580, 2018). "The short plasma half-life of natural somatostatin (~1.5 minutes) led to the development of analogs with higher stability, such as octreotide (Sandostatin; Novartis) (half-life of ~2 hours), that are used to treat pituitary and neuroendocrine tumors (NET)." (PMID 27177087, 2016). "Unfortunately, clinical attempts to treat breast cancer with available SST analogs, such as octreotide or lanreotide, successfully used in the treatment of pituitary and neuroendocrine tumors, have generated inconsistent, largely unsatisfactory clinical results in breast cancer patients." (PMID 26956474, 2016). "Furthermore, somatostatin and its derivates have several positive effects in the treatment of neuroendocrine neoplasms." (PMID 25723531, 2015). "Additionally, somatostatin and its analogues show antiproliferative actions, which make them useful as coadjuvant treatment especially for neuroendocrine tumors, apart from their usefulness in acromegaly." (PMID 24465589, 2014). "Furthermore, liposomes may be targeted by adding guidance molecules such as somatostatin for neuroendocrine tumors." (PMID 36979684, 2023). "Multiple studies are investigating the use of somatostatin antagonists with Lu177 radionucleotides that are internalized by the receptor-positive tumors cells and causes DNA damage resulting in cytotoxicity in other SSTR-positive tumors such as neuroendocrine tumors." (PMID 36033542, 2022). "Here, we investigated TNFα, CNTF, EGF, dermorphin, dynorphin 17, substance P, somatostatin, corticotropin-releasing hormone, and the native botulinum receptor-binding domain for their ability to direct the botulinum protease into a variety of neuroendocrine tumor cells." (PMID 23638840, 2013). "There are five SST subtypes (SST1‐5), which are expressed in different types of solid neoplasms and several neuroendocrine tumors (NETs), the most common subtypes being SST2 and SST5." (PMID 39473262, 2025). "Somatostatin (SST) plays a role in regulating cell growth and hormone secretion, making SSTRs a potential target for treating neuroendocrine neoplasms (NENs)." (PMID 39201255, 2024). "PSMA tracers are used in staging and re-staging prostate cancer, while somatostatin-targeting peptides (e.g. [68Ga]Ga-DOTA-TOC and -TATE) or [18F]DOPA are widely employed in neuroendocrine tumours." (PMID 39256216, 2024). "One of the important aspects of the pathogenesis of neuroendocrine tumors (NET), which are built with well or moderate differentiated tumor cells of NEN, is the interaction between ligands, such as somatostatin and its analogues, and somatostatin receptors." (PMID 38201544, 2023). "Both somatostatin (SST) and somatostatin receptors (SSTRs) are proteins with important functions in both physiological tissue and in tumors, particularly in neuroendocrine tumors (NETs)." (PMID 33085037, 2021).
neuroendocrine tumors (continued). "However, although somatostatin analogs proved to be effective treatments in aggressive pulmonary carcinoids, somatostatin receptor expression has no role in predicting the response to somatostatin analogs in thoracic well-differentiated neuroendocrine neoplasms." (PMID 33641055, 2021). "Somatostatin (SST) is a neuropeptide present in neurons, endocrine cells, and a wide range of neuroendocrine tumors (NETs)." (PMID 30151468, 2016). "The current evidence corroborates the role of [18F]FDG as the main player in molecular imaging; PSMA tracers are useful in staging and re-staging prostate cancer; somatostatin-targeting peptides (e.g. [68Ga]Ga- DOTA-TOC and -TATE) or [18F]DOPA are valuable in neuroendocrine tumours (NETs)." (PMID 39256216, 2024). "SST for its antiproliferation activity is known as a potential and effective therapeutic drug in tumour biology of neuroendocrine tumours but has not been explored in ovarian cancer." (PMID 38203605, 2023). "Two SST14-derived short cyclic SST analogues (lanreotide or octreotide) with improved stability and longer lifetime were developed as drugs to preferentially activate SSTR2 and treat acromegalia and neuroendocrine tumors." (PMID 35595746, 2022). "Gallium 68-tetraazacyclododecane-tetraacetic acid-octreotate ([68Ga]Ga-DOTA-TATE) is a selective somatostatin analogue ligand, which shows increased affinity for somatostatin receptor subtype (SSTR) 2 and has been used routinely for imaging neuroendocrine tumors with PET/CT." (PMID 34181114, 2021). "Neuroendocrine tumors (NETs), including PTs, express somatostatin receptors (SSTR1–5), which are G-protein coupled receptors bound and activated by the hormone somatostatin (SST)." (PMID 34205778, 2021). "The administration of somatostatin is frequently unsuccessful because unlike other neuroendocrine tumors many insulinomas do not express the necessary somatostatin receptors." (PMID 26986124, 2016). "While somatostatin can activate five somatostatin receptor subtypes (SSTR1-SSTR5), it has been shown that cyclic octapeptide octreotide selectively binds to the somatostatin subtype-2 (SSTR2) receptor (and, to a lesser extent, SSTR5), which is predominantly expressed in neuroendocrine tumours." (PMID 39451535, 2024). "The synthetic octapeptide analogs derived from the native somatostatin peptides SST-14 and SST-28, namely octreotate (TATE) or octreotide (TOC), are high affinity ligands for the somatostatin receptors (sstr), preferably subtypes 2 and 5, which are overexpressed on neuroendocrine tumors (NET)." (PMID 34832957, 2021). "On the other hand, in certain cases, and in particular for neuroendocrine tumors (a category of tumors where SSTRs are the most expressed), a benefit has been proven via two Phase III studies, which have greatly contributed to the fact that SST analogs are now used in clinical routine." (PMID 32887456, 2020). "In the later stages of the disease, the signaling between TGF-β and somatostatin is disrupted (somatostatin pathway is an antiproliferative pathway) forming an increased metastatic potential, in which TGF-β becomes an inducer rather than a suppressor of the transformation of neuroendocrine tumors." (PMID 36289922, 2022).